STAT3 (signal transducer and activator of transcription 3)
Diseases named in the same sentence as STAT3 in open-access papers (continued):
Sharing a sentence is not in itself a finding about the gene and the disease.
pancreatic cancer (continued). "In addition, one study reported that ginseng diol induced apoptosis in the pancreatic cancer cell lines PANC-1 and Patu8988 through the JAK2/STAT3 signaling pathway, limiting the progression of pancreatic cancer." (PMID 36313365, 2022). "CD59 has been reported to be highly expressed in patients with pancreatic cancer, and Pancreatic cancer-educated macrophages could up-regulate CD59 to protect cancer cells from CDC through the IL-6R/STAT3 signaling pathway." (PMID 35237592, 2022). "IL-6 enhances STAT3 phosphorylation in pancreatic cancer PANC-1 cell line." (PMID 36291659, 2022). "Summary of effects of STAT3 target-related inhibitors in pancreatic cancer." (PMID 36291659, 2022). "Furthermore, miR-301a was found to suppress the expression of SOCS5, which leads to JAK/STAT3 activation and is related to poor overall survival of pancreatic cancer patients." (PMID 35740894, 2022). "Although we have detected pSRC as a target of Niraparib, it remains to be determined whether Niraparib regulates other kinases activated in ovarian or pancreatic cancer cells to impact STAT3 activity and increase Niraparib’s antitumor effects." (PMID 36324587, 2022). "Furthermore, the decrease in pancreatic cancer cell proliferation caused by cucurbitacin I appeared to involve JAK2/STAT3 signalling pathway inhibition, and the use of JAK2/STAT3 activators effectively restored the inhibition." (PMID 35517401, 2022). "In this section, we mainly introduce the role of STAT3 in pancreatic cancer." (PMID 36291659, 2022). "STAT3 pathway plays a role in pancreatic cancer, in which IL-6 is the driving factor." (PMID 36291659, 2022). "Inhibiting STAT3 with small molecule inhibitors not only suppresses cancer growth, activates apoptosis, and inhibits angiogenesis, but it also has been shown to remodel the stroma of pancreatic cancers." (PMID 35886918, 2022). "The high expression of STAT3 in pancreatic cancer is positively correlated with the expression of VEGF and VEGF-C, indicating that STAT3 activation may be associated with angiogenesis in pancreatic cancer." (PMID 36291659, 2022). "We reviewed the relationship between STAT3 and pancreatic cancer and the latest results on the use of STAT3 inhibitors in pancreatic cancer, with the aim of providing insights and ideas around STAT3 inhibitors for a new generation of chemotherapeutic modalities for pancreatic cancer." (PMID 36291659, 2022). "Targeting IL-6 in acupuncture treatment of pancreatic cancer is a promising research direction, which may involve IL-6/STAT3 axis, DNMT1-induced SOCS3 methylation, NRP-1, etc." (PMID 36105933, 2022). "In this paper, we reviewed the relationship between STAT3 and pancreatic cancer and the latest results on the use of STAT3 inhibitors in pancreatic cancer, with the aim of providing insights and ideas around STAT3 inhibitors for a new generation of chemotherapeutic modalities for pancreatic cancer." (PMID 36291659, 2022). "It was reported that curcumin might block the activation of STAT3 at Tyr705 residue and downregulate gene expression, thus promoting cell inhibition of proliferation and apoptosis induction in pancreatic cancer cells." (PMID 34948455, 2021). "Likewise, STAT3 binds to DNA more effectively in the presence of Ref-1, and concurrent blockade of STAT3 and Ref-1 significantly inhibits the migration of pancreatic cancer cells." (PMID 33808242, 2021). "These collective findings may suggest that targeting the activation of STAT3 is a suitable strategy to prevent the initiation and progression of pancreatic cancer." (PMID 34491463, 2021). "It has been previously reported that STAT3 phosphorylation is a critical early event in the formation of precursor lesions for pancreatic cancer, and the conditional deletion of the Stat3 gene in mice expressing mutant KRAS in the pancreas blocked the development of PanINs." (PMID 34491463, 2021).
pancreatic cancer (continued). "Other putative STAT3 targets were DPYD, a gene encoding a key 5-FU-metabolizing enzyme, MUC1, which impacts on the response to radiotherapy in pancreatic cancer, and HIF1A, an established target of JAK-STAT signaling and previously reported as potential determinant of tumor radiosensitivity." (PMID 33530306, 2021). "Also, APX3330 treatment inhibits pancreatic cancer cell migration, but this was attributed to inhibition of STAT3 transcriptional activity." (PMID 34210327, 2021). "Therefore, our result implies that KRAS/p-STAT3 mediates the regulation of HPS expression in SUIT-2 pancreatic cancer cells." (PMID 33801246, 2021). "Similarly, inhibition of autophagy in pancreatic cancer stem cells also reduced the phosphorylation of STAT3." (PMID 34771150, 2021). "Owning to the key role of STAT3 and NF-κB in the regulation of the tumor microenvironment, further investigations also needed to explore whether N4 directly influences the pancreatic tumor microenvironment." (PMID 33420372, 2021). "Notably, both SHC1-engaged SRC and gp130-activated JAK2 signals increased the phosphorylation of STAT3 [Y705], a critical step in pancreatic cancer progression." (PMID 34921158, 2021). "The development of novel anticancer agents that directly target STAT3 may have potential clinical benefits for pancreatic cancer treatment." (PMID 33420372, 2021). "Inhibition of STAT3 signaling leads to apoptosis of pancreatic cancer cells." (PMID 34988078, 2021). "We next examined whether N4 inhibited pancreatic cancer in vivo mainly through STAT3, we carried out western blot and immunohistochemistry examinations of tumor samples." (PMID 33420372, 2021). "Meanwhile, our study firstly put forward that the high expression of TGM2 tracked with an immunosuppression-promoting phenotype and TGM2 is involved in the modulation of PD-L1 expression by regulating downstream transcription factor STAT3/NF-κB in pancreatic cancer cells." (PMID 33637086, 2021). "Stat3 is also aberrantly activated in a subset of pancreatic tumor tissues and cell lines." (PMID 33637083, 2021). "The targeted inhibition of STAT3 represents a promising therapeutic strategy for pancreatic cancer." (PMID 33420372, 2021). "Moreover, STAT3 has role in progression of pancreatic cancer precursor lesions, cell proliferation and metaplasia associated inflammation that subsequently leads to pancreatic ductal adenocarcinoma initiation." (PMID 34535145, 2021). "In pancreatic cancer, IL-6 induces the STAT3 signaling pathway and thus cancer cell proliferation." (PMID 34535145, 2021). "Furthermore, NFATs and signal transducer and activator of transcription 3 (STAT3) have been shown to be activated upon inflammation promoting inflammation-driven pancreatic cancer development." (PMID 33919156, 2021). "Inhibition of STAT3 by AG490 also decreased the invasion of human pancreatic cancer cells in vitro." (PMID 33098244, 2021). "On the other hand, in pancreatic cancer cells SMARCA2 activates epigenetically STAT3 signaling and may promote metastasis." (PMID 34874980, 2021). "N4 abrogated IL-6-stimulated STAT3 phosphorylation in pancreatic cancer cells." (PMID 33420372, 2021). "Moreover, we demonstrated that N4 exhibited potent antitumor activities in pancreatic cancer cells and mouse xenografts models through inhibiting STAT3 signaling." (PMID 33420372, 2021). "We found that after the treatment of pancreatic cancer BxPC-3 cells with 2-DG in different concentrations, with the concentration increasing, the protein level of P-STAT3 decreased significantly, and qPCR showed that STAT3 and its downstream target genes, VEGF and HIF1A were also decreased." (PMID 33607990, 2021). "Moreover, results in this experiment show remarkable synergistic effects observed in pancreatic cancer cells treated with selective STAT3 inhibitors, an EGFR/ErbB2 inhibitor, and a HIF-1α inhibitor." (PMID 33544704, 2021).
pancreatic cancer (continued). "It is widely known that KRAS is mutated in about 90% of pancreatic cancer cases and contributes to cancer cell proliferation via the MAPK pathway and STAT3 activation; thus, many studies are now investigating ways to target STAT3 as a therapeutic intervention for KRAS-mutant pancreatic tumors." (PMID 33801246, 2021). "A previous study also indicated that hyperglycemia could induce the phosphorylation of STAT3 and the expression of c-Myc proteins in pancreatic cancer." (PMID 34829591, 2021). "For example, the STAT3/Bmi1 pathway could be modulated by VPA to increase the sensitivity of gemcitabine to pancreatic cancer cells." (PMID 34568018, 2021). "We hypothesized that inhibition STAT3 would result in remodeling of desmoplastic stroma in pancreatic tumors." (PMID 33420372, 2021). "Interactions among Nrf2, NF-κB, and STAT3 signaling pathways, and their dysregulation, may play a key role in the development of cancer—including pancreatic cancer —driven by the inflammation process." (PMID 34944062, 2021). "STAT3 has emerged as a rationale drug target for pancreatic cancer." (PMID 33420372, 2021). "Moreover, berbamine enhanced the efficacy of gefitinib in pancreatic cancer cells and radiosensitivity for head and neck squamous cell carcinoma by inhibiting the STAT3 pathway." (PMID 33520087, 2021). "To test our hypothesis that IL-6 is responsible for the activation of the STAT3 pathway in pancreatic cancer cells, we performed experiments where we neutralized the IL-6 receptors (IL-6Rs) using the IL-6R neutralizing monoclonal antibody Tocilizumab." (PMID 34440697, 2021). "A dual inhibitor of STAT3 pathways induces death of tumor cells, indicating that suppression of the JAK2/STAT3 pathway may be a promising approach for the prevention and treatment of pancreatic cancer." (PMID 33029256, 2020). "Furthermore, SC-derived IL6 induced pancreatic cancer cells migration and invasion via activating STAT3 signaling in vitro." (PMID 32308766, 2020). "To identify whether STAT3 signaling is required for SC-mediated pancreatic cancer cell migration and invasion, we first determined whether the STAT3 pathway was activated in MIA PaCa-2 and AsPC-1 cells treated with co-cultured CM." (PMID 32308766, 2020). "In pancreatic cancer, abnormal activation of STAT3 is crucial for invasion and metastasis." (PMID 33029256, 2020). "Importantly, this study demonstrated that blocking STAT3 in vitro inhibited norepinephrine-induced pancreatic cancer cell migration, invasion, and PNI, and that treatment with a STAT3 phosphorylation inhibitor blocked PNI of pancreatic cancer cells in vivo." (PMID 33322770, 2020). "USP5 was also proved to mediate STAT3 signaling in pancreatic cancer cells." (PMID 33123271, 2020). "Moreover, STAT3 determines the development of features related to the malignancy of pancreatic cancer." (PMID 33158194, 2020). "Cucurbitacin B demonstrated anti-STAT3 effects in human pancreatic cancer cells and leukemia cells." (PMID 32545187, 2020). "Additionally, PPAR-γ and its agonists in combination with other drugs—such as type I interferons, gemcitabine, and COX-2 inhibitors—inhibit the survival of pancreatic cancer cells via IFN-β-induced activation of STAT-3, MAPK, and AKT." (PMID 31952344, 2020). "On a Kras-mutant background, hyperglycemia may contribute to pancreatic cancer progression via STAT3 phosphorylation and elevated MYC expression." (PMID 32609742, 2020). "Loss of SMAD4 induces constitutive activation of STAT3 in pancreatic cancer, which cooperates with non-canonical TGF-β signaling to promote cancer progression." (PMID 31952344, 2020). "The expressions of STAT3-directed genes in pancreatic cancer cells were also inhibited by EGCG." (PMID 32545187, 2020).
pancreatic cancer (continued). "However, recent reports demonstrated that APE1 regulates STAT3 in pancreatic cancer cell survival using E3330, an APE1 redox inhibitor." (PMID 32438692, 2020). "Likewise, S1PR1 signaling inhibition treatment resulted in inhibition of cell growth in pancreatic cancer cells via STAT3 pathway." (PMID 31438989, 2019). "Inhibiting the IL6/GP130/STAT3 pathway might therefore be a new therapeutic option for pancreatic cancer." (PMID 31139333, 2019). "Indeed, we were able to distinguish between normal pancreatic and pancreatic tumor tissue using G-STAT3 activity but were able to more specifically infer STAT3 activity using T- and E-STAT3." (PMID 31796877, 2019). "Therefore, we sought to develop a method that can distinguish between TF activities in the tumor and TME compartment to better characterize the multifaceted role of STAT3 in pancreatic cancer using a collection of gene expression datasets." (PMID 31796877, 2019). "As a confirmation of the potential efficacy of CSC-targeted treatment, clinical studies have demonstrated significant benefits in colorectal and pancreatic cancer with combination therapy using the STAT3 inhibitors napabucasin plus chemotherapy (NCT02231723, NCT02993731)." (PMID 31398893, 2019). "Furthermore, the miRNA miR-1181 also targets STAT3 and is downregulated in pancreatic cancer, predicting poorer overall survival." (PMID 31557897, 2019). "Finally, we utilized the compartment-specific STAT3 activities to evaluate the role of STAT3 in prognosis, immune infiltration, and metastasis in pancreatic cancer." (PMID 31796877, 2019). "In addition, high TME-derived STAT3 activity correlates with an immunosuppressive TME in pancreatic cancer, characterized by CD4 T cell and monocyte infiltration and high copy number variation burden." (PMID 31796877, 2019). "STAT3 is indispensable in normal pancreas development, and its overexpression may lead to pancreatic cancer." (PMID 31861404, 2019). "In addition, clinical trials have recently been initiated to test the efficacy of STAT3 pathway inhibitors in pancreatic cancer (Clinical Trial Identifiers NCT02767557, NCT02983578)." (PMID 31796877, 2019). "Additionally, since most pancreatic cancer patients are identified at an advanced stage, we were interested in the role of STAT3 during metastasis." (PMID 31796877, 2019). "Pancreatic cancer-educated macrophages could protect cancer cells from CDC by up-regulating CD59 via the IL-6R/STAT3 signaling pathway." (PMID 31685825, 2019). "Systematic analysis confirmed the regulatory roles of STAT3 in the TME of pancreatic cancer." (PMID 31796877, 2019). "We hypothesized that IL-6, secreted by TAMs, might induce the upregulation of CD59 in pancreatic cancer cells via STAT3 activation." (PMID 31685825, 2019). "On the other hand, CREB could also activate downstream STAT3 signaling pathways, as reported in pancreatic cancer cell growth." (PMID 30678730, 2019). "Moreover, STAT3 activation via phosphorylation exerts crucial roles in pancreatic cancer development." (PMID 31801946, 2019). "We first performed a systematic analysis to investigate the differential expression of all human TFs; our analysis included 1164 human TFs expressed in pancreatic cancer and confirmed STAT3 as one of the TFs being more highly expressed in the tumor microenvironment than in cancer cells." (PMID 31796877, 2019). "Other groups reported that the IL-6/JAK2 signaling pathway inhibits autophagy, via p-STAT3, which activates Bcl-2 to regulate the expression of Beclin 1 and VPS34, while in pancreatic cancer, IL-6 induces mitochondrial localization of p-STAT3 at Ser727, upregulating autophagy flux." (PMID 32565533, 2019). "Components of the pancreatic cancer pathway were extensively S-nitrosylated, such as v-raf-1 murine leukemia viral oncogene homolog 1 (Raf-1) and Signal transducer and activator of transcription 3 (STAT3)." (PMID 31801946, 2019).
pancreatic cancer (continued). "Rhein sensitizes human pancreatic cancer cells to EGFR inhibitors through inhibition of STAT3." (PMID 30674340, 2019). "Its role in pancreatic cancer is complex due to the diversity of cells that express STAT3." (PMID 31796877, 2019). "Subsequently, we transfected STAT3 siRNAs and siNC into pancreatic cancer cells." (PMID 31685825, 2019). "The inhibition of STAT3 signaling may be a promising strategy for attenuating chemoresistance in pancreatic cancer." (PMID 31244991, 2019). "Considering that STAT3 is the major tumor-promoting effector of IL-622,23, we focused on the STAT3 signal transduction pathway in promoting macrophage-mediated differentiation of pancreatic cancer cells." (PMID 31685825, 2019). "Notably, inhibition of HIC1-mediated STAT3–DNA binding affected invasion and metastasis of pancreatic cancer cells both in vitro and in vivo." (PMID 29914167, 2018). "More recently, Hu and colleagues confirmed HIC1’s repressor activity on STAT3 in pancreatic cancer." (PMID 29914167, 2018). "Moreover, TAM also directly induces CSC properties of pancreatic tumor cells by activating signal transducer and activator of transcription 3 (STAT3) and thus inhibits the antitumor CD8+ T lymphocyte responses in the chemotherapeutic response." (PMID 29681949, 2018). "In this vein, it has been shown that the STAT3 inhibitor phospho-valproic acid can also inhibit the mitochondrial STAT3 functions, and is able to decrease the STAT3 mitochondrial localization, correlating with the impaired growth of human pancreatic tumor xenografts." (PMID 30231582, 2018). "In support of this hypothesis are results showing that human pancreatic cancer cell lines expressing a mitochondrial targeted STAT3, that were orthotopically implanted into nude mice, were completely insensitive to P-V-mediated growth inhibition." (PMID 29914167, 2018). "Previous in vitro analyses showed that miR-155 inhibited cell migration of human cardiomyocyte progenitor cells via targeting of MMP-16 and, in pancreatic cancer cell, miR-155 plays an important role in the regulation of cell migration by modulating the STAT3 signaling pathway." (PMID 29161332, 2017). "As a novel inhibitor of GP130/STAT3 signaling, Bazedoxifene could suppress pancreatic cancer growth in vitro and in vivo and sensitize pancreatic cancer cells to paclitaxel and gemcitabine." (PMID 29100303, 2017). "STAT3 is the primary therapeutic target of CuB in pancreatic cancer." (PMID 29262554, 2017). "Interestingly, luteolin has been found to exert its anti-tumor effects by targeting and inactivating STAT3 in breast, liver, and pancreatic cancers." (PMID 28856117, 2017). "Treatment with OSU-A9 induced apoptosis, the down-regulation of Akt phosphorylation, the up-regulation of p38 phosphorylation, the inhibition of JAK and STAT3 phosphorylation, a reduction in pancreatic cancer cell aggressiveness, and the blocking of BxPC-3 xenograft growth in nude mice." (PMID 28418923, 2017). "Similarly, knockdown of STAT3 in T24 bladder cancer cells and Capan-1 pancreatic cancer cells dramatically decreased CCR1 mRNA levels, as revealed by RT-PCR and Q-PCR." (PMID 29212252, 2017). "CuB induces pancreatic cancer cell apoptosis through inhibition of STAT3 signaling." (PMID 29262554, 2017). "We deduce that the combination treatment with CuB and an ERK inhibitor against pancreatic cancer may be more effective than single drug treatment due to complementary effects on STAT3, ERK and EGFR activities." (PMID 29262554, 2017). "STAT3 activity is also necessary for pancreatic cancer cell invasion via MMP7." (PMID 27556697, 2016). "Furthermore, a positive feedback loop involving Reg3α-JAK/STAT-3 has been confirmed to accelerate pancreatic cancer cell growth." (PMID 27767186, 2016).